TNF (tumor necrosis factor)
Diseases named in the same sentence as TNF in open-access papers (continued):
Sharing a sentence is not in itself a finding about the gene and the disease.
breast carcinoma (continued). "The results of the sensitivity analysis showed that after excluding the studies with high heterogeneity, exercise significantly reduced the TNF-α levels in patients with breast cancer (WMD, -1.399 pg/ml; 95% CI, -1.718 to -1.080; P = 0.000)." (PMID 36482346, 2022). "BCL2A1 expression plays an important role in cell survival after CHCP treatment in breast cancer cells and is potentially regulated by TNF-alpha." (PMID 35260587, 2022). "Although not statistically significant, 6 h and 24 h sample groups showed an upward trend in expression, suggesting that TNF-alpha is involved in the induction of apoptosis in CHCP treated breast cancer cells." (PMID 35260587, 2022). "In breast cancer, researchers found that C5aR1-positive neutrophils secrete IL-1-β and TNF-α and they cooperatively activate ERK1/2 signal and phosphorylate WTAP at serine 341 to stabilize WTAP protein." (PMID 35251177, 2022). "ASCs/MSCs secrete various growth factors including IGF1 and EGF, and numerous cytokines such as leptin, IL6, adipsin, and TNFα, which stimulate proliferation and survival of breast cancer cells." (PMID 36010901, 2022). "In this study, we selected the ILK inhibitors OSU-T315 or TNF-α antibody in combination with GDC-0941 to study their therapeutic effects on breast cancer." (PMID 35477364, 2022). "The result shows a promising anti-cancer effect of BV6 alone as well as in combinational treatment with TRAIL and TNFα, compared to the lone treatment of TRAIL and TNFα in both breast cancer cell lines." (PMID 36358282, 2022). "The major focus of current studies is the regulatory mechanisms and therapeutic approaches of EMT for breast cancer in metastasis and invasion, mainly including miRNA and signaling pathways such as Wnt, Notch, TNF-α, NF-κB, and RTK." (PMID 35937944, 2022). "In this regard, TNF-α is found to increase the cytotoxicity of chemotherapy drugs and radiation therapy against breast cancer cells both in vitro and in vivo." (PMID 36234520, 2022). "The expression levels of IL-1β, IL-8, and TNF-α were significantly elevated in breast cancer tissues compared with that in normal appearing tissues." (PMID 35188865, 2022). "This study investigated the alteration of tumour necrosis factor (TNF-α) and interleukin-19 (IL-19) at different clinical disease stages, lymph node metastasis, and ductal carcinoma in women with breast cancer." (PMID 35928364, 2022). "The breast cancer MDA-MB-231 cell line elicits the production of proinflammatory cytokines TNF-α, IL-1beta, IL-6, IL-8, and IL-10." (PMID 36501201, 2022). "Programmed death-ligand 1 (PD-L1) switched tumor necrosis factor-α (TNF-α)-induced apoptosis to pyroptosis in breast cancer (BC) cells." (PMID 36387211, 2022). "GDC-0941 synergistically inhibits tumor growth with ILK inhibitor or TNF-α antibody and has good anti-breast cancer effects." (PMID 35477364, 2022). "Studies have shown that systemic inflammation – characterized by elevated levels of TNF-α, IL-6 and CRP – is associated with an increased risk of breast cancer progression and death." (PMID 36482346, 2022). "Previous studies reported a potential cytotoxic and anti-tumor effect, as well as an important role in breast cancer progression and the local recurrence of TNF-α." (PMID 36013233, 2022). "New research using nanoparticles for drug delivery into solid tumors has shown that TNF can act as a facilitator of a more efficient drug delivery into TME with breast cancer as a specific example." (PMID 36358688, 2022). "Up-regulation of ERβ significantly increases the expression of TNFα that induces apoptosis of breast cancer cells." (PMID 35593465, 2022). "Cytokines such as IL-6 and tumor necrosis factor-alpha (TNF-α) released by breast cancer cells can stimulate the expression of KDM2A in fibroblasts." (PMID 36291773, 2022). "The expression of AGP and IL-1β, IL-8 and TNF-α in breast cancer tissues were significantly higher than those in normal appearing tissues." (PMID 35188865, 2022).
breast carcinoma (continued). "Transcriptomic analysis of apigenin and quercetin uncovered that high-dose flavonoids activated TNF-α signaling, as verified through detecting inflammatory gene levels in breast cancer cells and RAW 264.7 macrophages." (PMID 35453307, 2022). "As expected, LPS and TNFα increased attachment of GFP-labeled breast cancer cells (HCC1937-GFP, MDA-MB-231-GFP and MDA-MB-468-GFP) and leukemia cells (Jurkat-GFP) to monolayer-cultured HUVECs." (PMID 35918322, 2022). "This is in good agreement with the fact that we see an increase in the concentration of TNF-α in saliva in advanced stages of breast cancer and in regional lymph nodes." (PMID 36286034, 2022). "TNFα is an essential pro-inflammatory cytokine commonly found in the tumor microenvironment and frequently involved in a pro-metastatic role in breast cancers." (PMID 35614362, 2022). "We found that 15 hub genes significantly correlated with the cancer pathway, IL-17 signaling pathway, TNF signaling pathway, breast cancer, and estrogen signaling pathway." (PMID 36405393, 2022). "TNF-α is found in the TME that is involved in all stages of breast cancer development, affecting tumor cell proliferation and survival, epithelial-to-mesenchymal transition (EMT), metastasis, and recurrence." (PMID 36303207, 2022). "DMF has been reported to suppress the constitutive and tumor necrosis factor α-induced activation of NF-κB and induce cell death in human breast cancer cells." (PMID 35955813, 2022). "Another investigation also showed the involvement of YAP and p65 NF-κB in increasing inflammation and breast cancer cell migration after TNF-⍺ stimulation." (PMID 36369000, 2022). "Progestins increased TNF alpha signaling, a cytokine involved in both lipid metabolism and breast cancer progression." (PMID 35406548, 2022). "There is evidence that low MCP-2 and TNF-α levels are correlated with a better prognosis and longer progression-free survival of breast cancer patients with bone metastasis." (PMID 35845981, 2022). "Secondly, a direct correlation was found between the concentration of IL-19 and TNF-α and tumour grade in breast cancer patients." (PMID 35928364, 2022). "We found that the mRNAs of the pro-inflammatory molecules Cxcl10 and IL-6 were upregulated in both cell types, while TNFα mRNA was upregulated only in mammary carcinoma cells when cells were transfected with poly(I:C)." (PMID 35737804, 2022). "One study indicated that the difference in TNF-α concentrations between breast cancer patients and controls was significant only for stage III cancers, consistent with the positive association that we observed only for large tumors." (PMID 35948877, 2022). "An MPR1-overexpressing breast carcinoma cell line demonstrated inherent sensitivity to in vitro cytotoxicity in response to TNF-α." (PMID 35814435, 2022). "The results showed that IL-1β, IL-8, and TNF-α expression levels in breast cancer tissues were elevated compared with those in the normal appearing tissues." (PMID 35188865, 2022). "Inflammatory CD4+ T cells drive breast cancer cells into senescence by releasing interferon-gamma and tumor necrosis factor-alpha, which directly bind to their receptors on cancer cells." (PMID 36467403, 2022). "A reduced responsiveness to stimulation of peripheral monocytes observed in TC patients is in line with earlier findings in breast cancer patients, showing an impaired production of IL-1β, IL-6 and TNFα in response to LPS35,36." (PMID 36257966, 2022). "As an example, Liu and colleagues identified a lncRNA NKILA which showed dramatic upregulation upon TNF-α treatment in breast cancer cells and suppressed breast cancer metastasis." (PMID 35842651, 2022). "Again, one pro-tumoral mechanism of TNF/TNFR2 signaling in breast cancer cells seems to be activation of the Akt pathway, this time resulting in upregulation of the DNA damage-repair protein poly(ADP-ribose) polymerase." (PMID 35681583, 2022).
breast carcinoma (continued). "The expression levels of IL-1β, IL-8, and TNF-α increased with progression through the clinical stages of breast cancer, and the differences were statistically significant (P = 0.03)." (PMID 35188865, 2022). "Some researchers believe that the effect of TNF-α on the growth of breast cancer is not only due to its influence on the immune response but also its ability to induce the expression of angiogenic factors." (PMID 35928364, 2022). "The data from normal breast tissue was corroborated by our results from experimental ER+ breast cancer where treatment with the pure anti-estrogen fulvestrant significantly decreased the levels of extracellular in vivo TNF." (PMID 35432372, 2022). "TNF-α is involved in the epithelial-to-mesenchymal transition and metastasis of breast cancer cells and represents an important target." (PMID 35672711, 2022). "An In vitro study in a breast cancer cell line found that CMTM1 eliminated TNF-α-induced apoptosis and eventually promoted breast cancer cell proliferation." (PMID 35252165, 2022). "Our finding of a positive association between TNF-α and breast cancer is consistent with several case–control studies showing higher serum TNF-α concentrations in breast cancer patient than controls." (PMID 35948877, 2022). "TNF-α is believed to stimulate the development of breast cancer by upregulating the expression of the transcriptional co-activator TAZ." (PMID 36234520, 2022). "VEGF, TNF-α, IL-1β, and IL-6 expression levels documented in breast cancer patients were increased in the biopsies tissues compared to normal tissues." (PMID 34572719, 2021). "Our previous studies have shown that TNF-α significantly enhanced the migratory and invasive potentials of breast cancer cells." (PMID 33572115, 2021). "A recent review described the mechanisms whereby chronic adipose tissue inflammation, with altered levels of adipokines and upregulation of cytokines (IL-1β, IL-6, and TNF-α), plays an important role in breast cancer prognosis." (PMID 34406210, 2021). "We used Tumor Immune Estimation Resource (TIMER) webserver to analyze the correlation between TNF-α and mitochondrial proteins in basal and luminal breast cancer patients." (PMID 33926547, 2021). "Given the increase in the migration of AWP1 silenced breast cancer cells in response to TNF-α, we next evaluated the effects of an AWP1 knockout on the TNF-α-mediated migration of MCF-7 breast cancer cells." (PMID 33816268, 2021). "For instance, pro-apoptotic activities were seen in both MCF-7 (ER-positive) and BT-549 (triple-negative) breast cancer cell lines, highlighting the potential dual role of TNF-α in breast cancer progression." (PMID 34944905, 2021). "In a striking contrast, TNFα induces a potent cytotoxic cell death in luminal (ER+) breast cancer cell lines which fail to upregulate A20 expression in response to TNF." (PMID 34943954, 2021). "Increased expression and secretion of TNFα and IL-6 as seen in our study is in line with other reports where breast cancer-EVs were shown to increase these cytokines." (PMID 34203762, 2021). "The TNF-α arrests cell cycle transition from G1 to S phase in mammary carcinoma cells and induces apoptosis in tumor cells." (PMID 35392343, 2021). "TNF-α is known to promote apoptosis in breast cancer cells, whereas NF-KB can inhibit apoptosis triggered by TNF-α." (PMID 35012116, 2021). "In our present study, we investigated the potential role of the AWP1 protein in breast cancer cells in response to TNF-α." (PMID 33816268, 2021). "We also confirmed that the proportion of macrophages expressing TNF-α or IL-12p40 following co-culture with viable 4T1 breast cancer cells was decreased." (PMID 33809707, 2021). "In this study, we report, for the first time to our knowledge, that TNF-α induces expression of IP-10 in MCF-7 breast carcinoma cells." (PMID 34572567, 2021).
breast carcinoma (continued). "The expression level of miR-23b is induced by the HER2/neu, EGF, TNF-α, and Blimp1, constitutively activated in breast cancer." (PMID 34777498, 2021). "Breast cancer, for example, is characterized by an elevated secretion of proinflammatory cytokines (IL-1, TNF-α, IL-6) or anti-inflammatory cytokines (IL-10), chemokines and chemokine receptors (CXCL8, CXCR4), and angiogenic factors (VEGF)." (PMID 35111484, 2021). "This study indicates the complex involvement of IκBα in the inflammatory response to TNF that is induced by radiation therapy in breast cancer." (PMID 34853340, 2021). "Overexpression of TNFα in engineered tumor cells (myeloma, fibrosarcoma, breast carcinoma) blocks their engraftment and growth in mice and creates a tumor suppressive microenvironment." (PMID 33957885, 2021). "In breast cancer, for example, TNFα was found to be expressed in patient tumors from early stages of tumor development and its elevated levels were associated with more advanced disease and with recurrence." (PMID 34201054, 2021). "In conclusion, the subcellular proteomics identifies the differential behavior of the ER/PR +ve and ER/PR −ve breast cancer cells in response to TNF-α." (PMID 33926547, 2021). "TNF-α is a cytokine that can induce apoptosis in a variety of tissues and cell types including breast cancer cells." (PMID 35012116, 2021). "TNF-α is one of the most important pro-inflammatory cytokines found in breast cancer, mainly secreted by M1 activated macrophages." (PMID 34388989, 2021). "The expression of inflammatory cytokines, such as interleukin-6 (IL6) and Tumor necrosis factor alpha (TNFα), have been related to an increase in invasiveness and a poor prognosis in breast cancer." (PMID 34573003, 2021). "Our previous studies showed that the treatment of breast cancer cells with TNF-α resulted in upregulation of CDKN1A/p21-dependent MMP9 expression/secretion which was found to be essential for cell migration." (PMID 33572115, 2021). "EMT of breast cancer cells is regulated by TGF-β/Smad-dependent pathway and activated by TNF-α/NF-κB/Twist, which both promote tumor metastasis and synergistically promote breast cancer cell migration." (PMID 35069596, 2021). "Pathway enrichment by KEGG of the PTs showed the regulation of ∼106 pathways, including the PI3K-Akt, breast cancer, and TNF signaling pathways, three main pathways that are regulated by tangeretin in metastasis signaling, based on the literature study." (PMID 34335799, 2021). "An in vivo breast cancer study demonstrated that tumour-derived MSCs (T-MSCs) and TNF-α-activated MSCs increased neutrophil tumour infiltration." (PMID 33860061, 2021). "Higher preoperative sCLU expression in breast cancer was associated with CAF resistance and TNF-alpha-induced apoptosis in breast cancer cells in vitro." (PMID 33356806, 2021). "Apart from the well-described antitumor activity, it has been shown that in melanoma, colorectal carcinoma, the breast cancer TNF-alpha increases the cells’ tumorigenic properties." (PMID 34283046, 2021). "ACSL1 regulates the TNFα- and LPS-induced GM-CSF production in breast cancer MDA-MB-231 cells, suggesting the role of ACSL1 in the regulation of growth-modulating cytokines or embryokines." (PMID 34299302, 2021). "Collectively, ours and other studies support the role of JNK/c-Jun axis in TNF-α-induced IP-10 expression in breast cancer or other cells." (PMID 34572567, 2021). "These adipocyte secretory factors (IL-6, TNF-α and leptin) were identified in acquired breast cancer drug resistance." (PMID 34812105, 2021). "Seminal work by Hung’s lab demonstrated that TNFα can increase PD-L1 expression in breast cancer cells by posttranscriptional regulation." (PMID 33540543, 2021).
breast carcinoma (continued). "In MDA-MB-468 (ER-negative) and SK-BR3 (HER2-positive) breast cancer cell lines, TNF-α induces growth." (PMID 34944905, 2021). "Results from our team demonstrate that TNFα expression and secretion by tumor cells is implicated in the resistance of HER2+ breast cancer cells to T-DM1 therapy by the upregulation of MUC4." (PMID 33540543, 2021). "TNF-α also exhibits a multi-function in breast cancer such as tumor markers, promotion, progression, and metastasis." (PMID 34287243, 2021). "We also found that serum ObR levels were positively correlated with serum CTLA-4 (p = 0.0056), TNF-α (p = 0.0025), PD-1 (p = 0.0023) levels as reported in breast cancer patients, and with serum PD-L1 levels (p = 0.0002)." (PMID 33644151, 2021). "Pro-inflammatory cytokines (IL-1β, IL-6, and TNF-α) not only play a potential role in the initiation of breast cancer (Section 3.2.1), but also in the progression of breast cancer." (PMID 34944905, 2021). "To gain further insight into how FOXO3a suppresses breast cancer metastasis, we examined the effect of FOXO3a on many microenvironmental genes, including TGF-β, TNF-α, EGF, FGF, PDGF, VEGF, and IGF, which have been implicated in promoting metastasis." (PMID 33262463, 2021). "Increasing the level of immune cell-like tumor-associated macrophage and soluble mediators like interleukin-1B (IL-1B) and tumor necrosis factor α (TNFα) are important for predicting poor prognosis in breast cancer." (PMID 33841325, 2021). "This study demonstrates that oestrogen deprivation increases breast cancer secretion of TNF, CCL5, IL-6, IL-8, and CCL22 and alters total human peripheral blood mononuclear cell migration in an in vitro assay." (PMID 34602068, 2021). "TNF-α is a crucial inflammatory cytokine in the tumor microenvironment that plays active role in all stages of breast cancer progression." (PMID 34569432, 2021). "Consistent with our current observations, several studies have suggested that TNF-α is frequently upregulated in breast cancer and exerts diverse functions in cancer-promoting processes such as cell migration." (PMID 33816268, 2021). "Serum NF-κB, TNF-α, sTRAIL, IL-6, PTX-3, PCT, and serum CRP levels were measured using enzyme-linked immunosorbent assay (ELISA) in 40 patients with breast cancer, 40 patients with colon cancer and 30 healthy controls." (PMID 33776564, 2021). "Annexin A2 from breast cancer exosomes can stimulate the secretion of IL-6 and TNF-α by inducing macrophage-mediated p38 MAPKs." (PMID 34485600, 2021). "Breast cancer patients present an increase in pro-inflammatory cytokines (IL-1β, IL-6, IL-18, TNFα and IFNγ)." (PMID 34201776, 2021). "TNF-α modulated metabolic reprogramming favors survival and proliferation of more aggressive ER/PR −ve breast cancer cells." (PMID 33926547, 2021). "Tumor proinflammatory cytokine, TNFα, efficiently transforms BMSCs into TA-MSCs and promotes tumor growth in lymphoma, melanoma, and breast carcinoma." (PMID 33889575, 2021). "Conversely, PrPC was shown to activate NFκB-dependent transcription in breast cancer cells, or to be necessary for the TNFα-dependent activation of NFκB in melanoma M2 cells, thereby delineating a bidirectional link between PrPC and NFκB." (PMID 34638517, 2021). "In concert with this, the study showed that also the tumor necrosis factor (TNF) levels in breast cancer tissue and liver cancer cells of rats exposed to the diet were diminished by the ginger extract." (PMID 34203813, 2021). "Our finding that TNF-α per se induces IP-10 in breast cancer cells is noteworthy since IP-10 is a potent leukocyte chemoattractant for activated monocytes/macrophages, T cells, and dendritic cells." (PMID 34572567, 2021). "The authors measured TNFα serum concentration from metastatic breast cancer patients receiving chemotherapy and found that a serum TNFα concentration of greater than 6.2 pg/mL correlated with a greater than 50% change of breast cancer survival." (PMID 33445695, 2021).